CYP1A2 (cytochrome P450 family 1 subfamily A member 2)
Diseases named in the same sentence as CYP1A2 in open-access papers (continued):
Sharing a sentence is not in itself a finding about the gene and the disease.
breast carcinoma (continued). "While the role of CYP1A2 rs762551 with respect to breast cancer risk seems weak or non-significant, unless coffee consumption was taken into account." (PMID 27029552, 2016). "Fourthly, beside breast cancer, there are no genome-wide association studies of the effects of CYP1A2 polymorphisms on cancer risk." (PMID 26865042, 2016). "A recent study reported that coffee reduced the risk of breast cancer in BRCA1 carriers with the CYP1A2*1F C-allele but not in those with the CYP1A2*1F A/A genotype." (PMID 18813311, 2008). "Until larger studies with the ability to look at gene-gene and gene-environment interactions are completed, it will remain unclear to what extent the variant alleles for CYP1A2 and COMT affect a woman's lifetime risk of developing breast cancer." (PMID 17295924, 2007). "However according to our statistical significant result, we propose that the CC genotype of the rs762551 SNP of the CYP1A2 gene may act as protective factor against breast cancer progression and development." (PMID 31477036, 2019). "This study identified a new potential AI-treatment predictive marker in CYP1A2 rs762551 for early breast cancer events, and the results indicate that CYP1A2 rs762551 in combination with CYP19A1 rs4646 or AhR Arg554Lys may yield even better treatment prediction." (PMID 27029552, 2016). "This study highlights significant genetic alterations in CYP1A2-rs17861162 and ADSL-rs3788579 SNPs among breast cancer patients in North-West Iran, suggesting their potential as diagnostic and prognostic biomarkers." (PMID 38433141, 2024). "Breast cancer can be prevented by eating foods that change the activity of certain cytochrome P450 enzymes, including CYP1A1, CYP1A2, CYP1B1, CYP2B6, CYP3A4, CYP19A1, and CYP24A1." (PMID 36571647, 2022). "Additionally, a case-control study proposed that variations in the cytochrome P450 1A2-164 A/C (CYP1A2) or N-acetyltransferase 2 (NAT2) acetylator genotype may affect the relationships between consumption of red meat or meat-related mutagens and breast cancer risk." (PMID 36230700, 2022). "It was reported that CYP1A2, a phase I/II metabolizing enzyme, was upregulated in DOX-resistant breast cancer cells." (PMID 34799689, 2021). "Eupatorin inhibits CYP1A2 and the in vitro proliferation of MDA-MB-468 human breast cancer cells that express CYP1A1." (PMID 32425779, 2020). "Altogether, the CYP1A2 SNP (rs17861162) results in an alteration of the allelic balance observed in women without breast cancer." (PMID 38433141, 2024). "CYP1A2 and CYP3A4 protein expression was shown in 168 breast cancer tissues." (PMID 28418906, 2017). "To the best of our knowledge, we are the first to analyse the association of the four CYP450 SNPs, including rs11636419, rs17861162, and rs2470890 in the CYP1A2 gene and rs12333983 in the CYP3A4 gene, with the clinicopathological features and prognosis of breast cancer patients." (PMID 28418906, 2017). "The known and possible functional roles of this SNP in breast cancer have not yet been revealed precisely, however, CYP1A2 plays a prominent role in the activation of pre-carcinogens through metabolic processes and SNPs can alter the activity of the corresponding proteins." (PMID 38433141, 2024). "Some similar studies showed that CYP1A2 and CYP3A4 could be induced in human hepatocytes exposed to BDE-99 and BDE-209, and these results were also supported by the study using human MCF-7 breast cancer cells exposure to PBDEs." (PMID 23554634, 2010).
hepatocellular carcinoma (21 papers, 2010 to 2025). A malignant tumor that arises from hepatocytes. "This study systematically elucidates the potential mechanisms of AAI, an environmental pollutant, in inducing hepatocellular carcinoma, identifying key targets including CYP1A2, ESR1, and AURKA." (PMID 40864066, 2025). "For the biomarkers identified from the mRNA data, CYP1A2 has been identified as a potential cancer suppressor and an independent prognostic marker for patients with hepatocellular carcinoma." (PMID 38678587, 2024). "In hepatocellular carcinoma, CYP1A2 inhibits cancer progression through antagonizing HGF/MET signaling." (PMID 36110953, 2022). "Since CYP1A2 is a hepatic enzyme, we selected liver-viral (hepatocellular carcinoma) to compute the cancer driver scores." (PMID 33654112, 2021). "In contrast, lansoprazole, omeprazole, and pantoprazole induced Cyp1a1, Cyp1a2, Cyp2b and Cyp3a in primary human hepatocytes, human liver, human hepatoma cells and rat liver." (PMID 24846271, 2014). "The next step was to verify whether IP6 has the same effect in HepG2, a commonly used hepatoma cell line, considering that HepG2 has a different expression profile compared to hepatocytes, with an undetectable expression of the CYP1A2 gene." (PMID 38612422, 2024). "A similar phenomenon mediated by another CYP450 family member, CYP1A2, has been observed in hepatocellular carcinoma, in which CYP1A2 catalyzes metabolic transformation from 17β-estradiol to 2-methoxyestradiol, thus markedly inhibiting proliferation and triggering apoptosis." (PMID 35887201, 2022). "Together, these findings propose CYP1A2 as a possible candidate for hepatocellular carcinoma and provide structural insights into how cancer driver nsSNPs could affect protein structure, heme stability and interaction network." (PMID 33654112, 2021). "CYP3A4 and CYP1A2 have been shown to be efficient in metabolizing aflatoxin B1 (AFB1), a carcinogen implicated in the etiology of hepatocellular carcinoma (HCC)." (PMID 39682707, 2024). "On the other hand, the low activity or downregulation of CYP1A2 influenced by the SNP would result in the progression of hepatocellular carcinoma (HCC)." (PMID 33192522, 2020). "When hepatoma cells were treated with IL-6, the levels of CYP1A1, CYP1A2, CYP2B6, CYP3A3, and CYP3A4 mRNAs were markedly suppressed, as well as activities of CYP1A2, CYP2B6, and CYP3A4." (PMID 35185562, 2022). "Specifically, studies in mouse hepatoma cells proved PB to be a weak ligand of AhR, as well as an inducer of CYP1A1 and benzo[a]pyrene hydroxylase activity; on the contrary, CYP1A2 was regulated through molecular mechanisms independent from AhR." (PMID 35408925, 2022). "Cytochrome P450 1A2 (CYP1A2) was significantly down-regulated in hepatocellular carcinoma (HCC)." (PMID 33500715, 2021). "Since KET induced CYP1A1 mRNA and protein in human hepatoma cells HepG2, we examined a capability of KET to induce CYP1A1 and CYP1A2 mRNA and protein in primary human hepatocytes, a more physiological and metabolically competent cell model." (PMID 25000292, 2014). "We also evaluated CYP1A1, CYP1A2, NQO1, and UGT1A1 expression following leflunomide exposure in HepG2 human hepatoma cells." (PMID 20957046, 2010). "Another study showed that growing placenta MSCs on a 3D fluidized bioreactor and treating them with hepatoma-derived C3A significantly improved ALB, urea secretion, and increased CYP1A2 and CYP3A4 that indicated significant differentiation of SCs into hepatocytes." (PMID 36685673, 2023). "For instance, certain liver-specific functions, including the metabolism by at least CYP1A2 and CYP3A4, are enhanced when cultivating hepatoma cells within three-dimensional alginate scaffolds, different co-culture systems or on PHBV microspheres to stimulate liver microarchitecture." (PMID 24788541, 2014).
schizophrenia (18 papers, 2013 to 2026). A major psychotic disorder characterized by abnormalities in the perception or expression of reality. "Moreover, upregulation of miR-27b, miR-200c, miR-21 and miR-122 and downregulation of miR-132 associated with the silenced activity of CYP1A2 can have therapeutic potential in schizophrenia." (PMID 39812050, 2025). "In a prospective study of 37 patients with schizophrenia or schizoaffective disorder treated with olanzapine, the influence of smoking and CYP1A2 polymorphisms on the disposition of olanzapine and its metabolite 4′-N-desmethylolanzapine in serum and cerebrospinal fluid was investigated." (PMID 32906709, 2020). "Several reports suggest a possible link between CYP1A2 and schizophrenia or the response to antipsychotic drugs, although the evidence remains inconclusive." (PMID 39812050, 2025). "DNA was isolated from the peripheral blood samples of 27 patients with schizophrenia receiving clozapine maintenance treatment, and the pharmacokinetics‐related genes (CYP1A2, CYP2B6, CYP2C19, CYP2D6, CYP3A5, ABCG2, and SLCO1B1) were genotyped." (PMID 40740505, 2025). "Approximately 18% of the antipsychotics used to treat schizophrenia, including clozapine, olanzapine, trifluoperazine and thiothixene are major substrates of CYP1A2." (PMID 39812050, 2025). "In summary, an inverse connection between CYP1A1 and miR-21; CYP1B1 with miR-27b and miR-200c; and CYP1A2 with miR-122 points to a miRNA-CYP enzyme regulatory network in schizophrenia that can be readily detected in the blood." (PMID 39812050, 2025). "The objective of this study was to explore the correlation between DRD2, HTR2A, SLC6A4, CYP1A2, and ABCB1 polymorphisms and clozapine response in 100 patients with Treatment-Resistant Schizophrenia." (PMID 38540209, 2024). "This drug, an antipsychotic used in the treatment of refractory schizophrenia with frequent severe side effects, is mainly metabolized by CYP1A2, resulting in two metabolites with different toxicological and pharmacological profiles." (PMID 37509119, 2023). "In patients with schizophrenia, clozapine dosage is influenced by CYP1A2 activity, and tacrine metabolism is primarily dependent on the activity of CYP1A2 and CYP3A4 enzymes." (PMID 37759556, 2023). "The main aim of the present study was to evaluate the contribution of CYP1A2 and CYP2D6 genetic variability as well as of CYP1A2 expression to olanzapine exposure in patients with schizophrenia and bipolar disorders." (PMID 37898643, 2023). "CYP1A2 interacts with multiple psychiatric medications (e.g., clozapine, escitalopram, and paroxetine) indicated for MD, schizophrenia, anxiety disorders, and post-traumatic stress disorder." (PMID 34603368, 2021). "Smoking additionally has a significant effect on the pharmacological management of schizophrenia, as metabolism clozapine and olanzapine is increased due to induction of CYP1A2 activity." (PMID 34938579, 2021). "The CYP1A2 member is of relevance in schizophrenia patients, as it plays a significant role in the metabolism of both clozapine and olanzapine." (PMID 34938579, 2021). "Except for CYP1A2 in patients taking clozapine, which we discussed earlier, the mechanisms by which variation within these pharmacogenes could influence schizophrenia severity are unclear." (PMID 40347835, 2025). "Moreover, CYP1A2 is involved in the metabolism of medicines about 20% of clinically metabolized drugs such as those used in long-term treatment of schizophrenia and depression." (PMID 26977174, 2016). "We investigated the effects of age, sex, and genetic polymorphisms in CYP isoforms (CYP1A2, CYP2B6, CYP2C19, CYP2D6, and CYP3A5) and drug transporters (ABCG2 and SLCO1B1) on the plasma concentrations of clozapine, N‐desmethylclozapine, and clozapine N‐oxide in Japanese patients with schizophrenia." (PMID 40740505, 2025).
schizophrenia (continued). "Finally, we did not observe evidence for an association between CYP1A2 activity score and either the positive or negative schizophrenia symptom dimensions." (PMID 40347835, 2025). "Additionally, miR-27b, miR-200c, miR-21 and miR-122 and miR-132 may serve as ideal theranoMiRNAs in schizophrenia, particularly when analysed in conjunction with CYP1A2, CYP1B1 and CYP1A1 activities." (PMID 39812050, 2025). "Adult patients with schizophrenia will be randomized (2: 1) to receive PGx-assisted treatment (drug and regimen selection depending on the results of single-nucleotide polymorphisms in genes DRD2, HTR1A, HTR2C, ABCB1, CYP2D6, CYP3A5, and CYP1A2) or the standard of care." (PMID 38598465, 2024). "It has been reported that CYP1A2 genotype is involved in the rate-limiting step in the metabolism of many drugs such as caffeine in myocardial infarction, theophylline in asthma, and clozapine in schizophrenia, as well as in the bioactivation of procarcinogens." (PMID 24282434, 2013). "In patients with schizophrenia (N = 96), development of clozapine concentration-dependent metabolic side-effects was found to be associated with pharmacokinetic variability related to CYP3A4 but not to CYP1A2 expression." (PMID 33277605, 2020).
myocardial infarction (16 papers, 2006 to 2025). Gross necrosis of the myocardium, as a result of interruption of the blood supply to the area, as in coronary thrombosis. "Increased risk of myocardial infarction and arterial hypertension has been found in individuals who carry a functional variant of cytochrome P450 1A2 (CYP1A2), which makes them less effective in metabolizing caffeine." (PMID 34370111, 2021). "The CYP1A2 enzyme has been highly implicated in several pathologies, including increased carcinogenesis, myocardial infarction, and insulin resistance." (PMID 34442334, 2021). "Bleeding events after taking clopidogrel are significantly more common among black CYP1A2*1C carriers with acute myocardial infarction." (PMID 36213502, 2022). "Carriers of the CYP1A2*1F allele have been demonstrated to be at higher risk of nonfatal myocardial infarction following intake of caffeinated coffee." (PMID 28817085, 2017). "In a case-control study, high coffee intake was associated with increased risk of non-fatal myocardial infarction only in individuals with the CYP1A2*1F allele, suggesting that caffeine is involved in the coffee-CHD association." (PMID 25946046, 2015). "In addition, coffee intake is correlated with a risk of nonfatal myocardial infarction; this correlation is believed to be influenced by CYP1A2, which is related with the development of RA in Korea." (PMID 37474895, 2023). "However, in a study of coffee intake, CYP1A2 genotype and risk of myocardial infarction coffee was associated with an increased risk of nonfatal myocardial infarction only in participants regarded as slow metabolizers of caffeine." (PMID 20175915, 2010). "Recently Cornelis and co-workers determined whether CYP1A2 genotype modifies the association between intake of caffeinated coffee and the risk of nonfatal myocardial infarction." (PMID 17205121, 2006).
Hypertension (13 papers, 2011 to 2025). The presence of chronic increased pressure in the systemic arterial system. "If there is a polymorphism in CYP1A2, the elimination rate is considerably higher, so the consumption of coffee mainly, chocolate, and/or tea can lead to hypertension, insomnia, altered glucose levels, etc.." (PMID 40648913, 2025). "Caffeine is primarily metabolized by cytochrome P450 enzyme 1A2 (CYP1A2), the activity of which is partly inherited, so people with slower metabolism are at increased risk of hypertension." (PMID 39119461, 2024). "CYP1A2 modulated the effect of caffeinated coffee on myocardial infarction and its polymorphism was associated with hypertension." (PMID 34391463, 2021). "Our results indicate the possibility of a protective effect of coffee on hypertension and confirm the joint role of coffee and CYP1A2 rs762551 polymorphism on hypertension." (PMID 34391463, 2021). "Coffee drinking, particularly among individuals with the CYP1A2 rs762551 AC + CC genotype was associated with lower odds of hypertension." (PMID 34391463, 2021). "Grouped analyses revealed an inverse association between hypertension and coffee drinking, particularly among individuals with the CYP1A2 rs762551 AC + CC genotype." (PMID 34391463, 2021). "Research on hypertension based on CYP1A2 polymorphism and coffee intake in Taiwanese is seemingly rare." (PMID 34391463, 2021). "GWAS have identified the region nearby CYP1A2 as being robustly associated with blood pressure and hypertension." (PMID 23049672, 2011). "Furthermore, a recent study has shown an increased risk of hypertension and renal dysfunction with heavy coffee intake, but only among individuals with the AC and CC genotypes of CYP1A2 at rs762551." (PMID 38732608, 2024). "Since hypertension is CYP1A2 variants risk factor for stroke, the study suggests that CYP1A2 variants may be indirectly associated with the development of stroke." (PMID 37481659, 2023). "Moreover, the association of hypertension with coffee drinking was also confirmed to vary according to CYP1A2 genotypes." (PMID 34391463, 2021). "Similarly, the risk of sustained hypertension has been associated with CYP1A2*1F polymorphisms in a cohort of stage I hypertensive individuals." (PMID 28817085, 2017). "Finally, as the CKS-ULK3-CYP1A2 locus contains many other genes than CYP1A2, further work is needed to know which gene is causally associated with blood pressure and hypertension." (PMID 23049672, 2011). "This cohort study assesses whether CYP1A2 genotype modifies the association between caffeine intake and kidney dysfunction among untreated individuals in Italy aged 18 to 45 years with stage 1 hypertension." (PMID 36701157, 2023). "We examined the relationship between hypertension and coffee drinking based on CYP1A2 rs762551 SNP in Taiwanese adults." (PMID 34391463, 2021). "CYP1A2 polymorphisms have been previously associated with disease susceptibility such as cancers, porphyria cutanea tarda, spontaneous abortion, but never with hypertension until these recent GWAS." (PMID 23049672, 2011). "Therefore, we could not determine the interaction between CYP1A2 polymorphism and caffeine or decaffeinated coffee on hypertension risk." (PMID 34391463, 2021). "The commonly prescribed drugs for hypertension (Propranolol, Metoprolol, Telmisartan, Losartan) and T2DM (Glimepiride, and Pioglitazone) shares the same drug metabolizing enzymes (CYP1A2, CYP3A4, CYP2C9, and CYP2D6)." (PMID 34115763, 2021).